GTF2H1 (general transcription factor IIH subunit 1)
Description:
Component of the general transcription and DNA repair factor IIH (TFIIH) core complex, which is involved in general and transcription-coupled nucleotide excision repair (NER) of damaged DNA and, when complexed to CAK, in RNA transcription by RNA polymerase II. In NER, TFIIH acts by opening DNA around the lesion to allow the excision of the damaged oligonucleotide and its replacement by a new DNA fragment. In transcription, TFIIH has an essential role in transcription initiation. When the pre-initiation complex (PIC) has been established, TFIIH is required for promoter opening and promoter escape. Phosphorylation of the C-terminal tail (CTD) of the largest subunit of RNA polymerase II by the kinase module CAK controls the initiation of transcription.
Synonyms: BTF2; P62; TFIIH; TFB1
Tractability: Small molecule: a structure with a bound ligand is known. PROTAC: UniProt records ubiquitination sites on it; ubiquitination databases record sites on it; its protein half-life has been measured.
Gene: Protein-coding gene on chromosome 11 (18,322,276 to 18,367,045, forward strand). Ensembl gene ENSG00000110768.
Subcellular location: Nucleus
Subcellular location (Human Protein Atlas): Nucleoplasm
Pathways (Reactome):
Gene expression (Transcription): Formation of RNA Pol II elongation complex; Formation of the Early Elongation Complex; NoRC negatively regulates rRNA expression; RNA Pol II CTD phosphorylation and interaction with CE; RNA Polymerase I Promoter Escape; RNA Polymerase I Transcription Initiation; RNA Polymerase I Transcription Termination; RNA Polymerase II Pre-transcription Events; RNA Polymerase II Promoter Escape; RNA Polymerase II Transcription Elongation; RNA Polymerase II Transcription Initiation; RNA Polymerase II Transcription Initiation And Promoter Clearance; RNA Polymerase II Transcription Pre-Initiation And Promoter Opening
Disease: Formation of HIV elongation complex in the absence of HIV Tat; Formation of HIV-1 elongation complex containing HIV-1 Tat; Formation of the HIV-1 Early Elongation Complex; HIV Transcription Initiation; RNA Pol II CTD phosphorylation and interaction with CE during HIV infection; RNA Polymerase II HIV Promoter Escape; Tat-mediated elongation of the HIV-1 transcript; Transcription of the HIV genome
DNA Repair: Dual Incision in GG-NER; Dual incision in TC-NER; Formation of Incision Complex in GG-NER; Formation of TC-NER Pre-Incision Complex; Gap-filling DNA repair synthesis and ligation in TC-NER; Transcription-Coupled Nucleotide Excision Repair (TC-NER)
Metabolism of RNA: mRNA Capping
Gene Ontology:
Molecular function: nuclear thyroid hormone receptor binding; protein binding
Biological process: positive regulation of DNA-templated transcription; transcription by RNA polymerase II; transcription initiation at RNA polymerase II promoter; DNA repair; hormone-mediated signaling pathway; nucleotide-excision repair; regulation of cyclin-dependent protein serine/threonine kinase activity; transcription by RNA polymerase I; DNA-templated transcription
Cellular component: nucleoplasm; transcription factor TFIIH core complex; transcription factor TFIIH holo complex; nucleus
Genetic constraint (gnomAD): Loss-of-function variants: 5 observed, 25.28 expected, observed/expected ratio (o/e) 0.2, 90% interval 0.1 to 0.42. The upper end of that interval is the gene's LOEUF score, 0.42, which puts it in group 1 of 6, group 1 being the genes least tolerant of losing a copy. Missense variants: 185 observed, 273.76 expected, observed/expected ratio (o/e) 0.68, 90% interval 0.6 to 0.76. Synonymous variants: 93 observed, 90.81 expected, observed/expected ratio (o/e) 1.02, 90% interval 0.87 to 1.22.
Homologues: Orthologues: macaque GTF2H1 (99% identical), dog GTF2H1 (98% identical), pig GTF2H1 (98% identical), mouse Gtf2h1 (97% identical), rat Gtf2h1 (97% identical), chimpanzee GTF2H1 (94% identical), guinea pig GTF2H1 (92% identical), tropical clawed frog gtf2h1 (84% identical), zebrafish gtf2h1 (77% identical), Drosophila melanogaster Tfb1 (48% identical), Caenorhabditis elegans gtf-2H1 (31% identical).
Diseases named in the same sentence as GTF2H1 in open-access papers:
GTF2H1 is named in the same sentence as 14 diseases in open-access papers, as found by Europe PMC text mining. Sharing a sentence is not in itself a finding about the gene and the disease. The quoted sentences say what the papers report.
lung carcinoma (3 papers, 2010 to 2023). "Certain polymorphisms/haplotypes of GTF2H1 have been associated with increased susceptibility to lung cancer." (PMID 37260986, 2023). "Associations between RAD54L2 and GTF2H1 polymorphisms and the risk of lung cancer were evaluated under different genetic models." (PMID 36384536, 2022). "Stratified analysis found that associations of RAD54L2 rs11720298, RAD54L2 rs4687592, RAD54L2 rs9864693 and GTF2H1 rs4150667 with lung cancer risk were found in subjects aged ≤ 59 years." (PMID 36384536, 2022). "GTF2H1 rs4150667 was associated with a decreased risk of lung cancer in subjects with BMI ≤ 24 kg/m2." (PMID 36384536, 2022). "Rs3802967 is located in the 5’-UTR region of GTF2H1 gene, and the luciferase activity experiments displayed that rs3802967 T allele was related to the enhanced expression of GTF2H1 in lung cancer cells." (PMID 36384536, 2022). "A previous study has showed that variants of GTF2H1 rs3802967 and rs4150667 are also significantly associated with the risk of lung cancer in the southern Han Chinese population." (PMID 36384536, 2022). "Among subjects with BMI ≤ 24 kg/m2, GTF2H1 rs4150667 (OR = 0.18, p = 0.008) contributed to a lower risk of developing lung cancer." (PMID 36384536, 2022). "Variants of the GTF2H1 gene have been recently found to be associated with lung cancer in a Chinese population." (PMID 21124955, 2010). "Our finding will provide evidence that age, BMI, smoking, and drinking might be associated with the effects of RAD54L2 and GTF2H1 variants on lung cancer susceptibility." (PMID 36384536, 2022). "This study may increase the understanding the effects of of RAD54L2 and GTF2H1 polymorphisms on the occurrence of lung cancer." (PMID 36384536, 2022). "Moreover, a risk-increasing association was found between GTF2H1 rs4150667 and lung cancer risk in subjects aged ≤ 59 years, while GTF2H1 rs4150667 was associated with a reduced risk of developing lung cancer in subjects with BMI ≤ 24 kg/m2." (PMID 36384536, 2022). "This study may increase the understanding of the effect of RAD54L2 and GTF2H1 polymorphisms on lung cancer occurrence." (PMID 36384536, 2022). "One research has found that rs3802967 and rs4150606 in the GTF2H1 gene may increase the risk of lung cancer, and rs4150667 in the GTF2H1 gene variant may reduce the risk of lung cancer." (PMID 36384536, 2022). "Among subjects with BMI ≤ 24 kg/m2, GTF2H1 rs4150667 had the lower risk of developing lung cancer." (PMID 36384536, 2022). "Besides, rs4150606 on GTF2H1 increased the risk of lung cancer." (PMID 36384536, 2022). "So, the genetic polymorphisms of GTF2H1 may be involved in the pathogenesis of lung cancer." (PMID 36384536, 2022). "In the follow-up studies, we will improve relevant information and adjust risk factors to further analyze the correlation of GTF2H1 and RAD54L2 with the risk of lung cancer." (PMID 36384536, 2022). "The study aimed to assess the correlation between single nucleotide polymorphisms (SNPs) in DNA repair gene (GTF2H1 and RAD54L2) and the risk of lung cancer." (PMID 36384536, 2022). "The influence of GTF2H1 and RAD54L2 polymorphisms on lung cancer susceptibility was assessed using logistic regression analysis by calculating odds ratios (ORs) and their corresponding 95% confidence intervals (CIs)." (PMID 36384536, 2022). "Especially, among subjects aged ≤ 59 years, RAD54L2 rs11720298 was related to a reduced susceptibility to lung cancer, while the risk-increasing associations were found for RAD54L2 rs4687592, RAD54L2 rs9864693 and GTF2H1 rs4150667." (PMID 36384536, 2022). "Here, nine polymorphisms in GTF2H1 and RAD54L2 were selected and genotyped to explore their impact on the risk of lung cancer in the Chinese Han population." (PMID 36384536, 2022). "The study found that the expression of GTF2H1 was down-regulated in lung cancer tissues." (PMID 36384536, 2022).
lung carcinoma (continued). "Five SNPs in GTF2H1 and four SNPs in RAD54L2 in 506 patients with lung cancer and 510 age-and gender-matched healthy controls were genotyped via the Agena MassARRAY platform." (PMID 36384536, 2022).
liver cancer (2 papers, 2021 to 2024). An epithelial or non-epithelial malignant neoplasm that arises from the liver. "GTF2H1 (general transcription factor IIH subunit 1) is identified as a DNA repair-related gene that can predict liver cancer." (PMID 39202384, 2024). "However, in our study, the results of multivariate Cox regression analysis showed that GTF2H1 has the greatest impact on OS of patients with liver cancer." (PMID 33516217, 2021). "Moreover, among of them, RFC4, ZWINT, UPF3B, NCBP2, ADA, SF3A3 and GTF2H1 are independent prognostic indicators of liver cancer." (PMID 33516217, 2021).
anemia (1 paper, 2017). A reduction in the number of red blood cells, the amount of hemoglobin, and/or the volume of packed red blood cells. "We also found rs4150558 (χ2 test P = 1.24 × 10–5; OR = 4.39, 95%CI:1.37–14.08, P = 0.013) in GTF2H1 were significantly associated with anemia in patients receiving NP regimen." (PMID 28924235, 2017). "rs4150558 in GTF2H1 was significantly associated with anemia in all patients, the same effect was also observed in not only SCC but also subgroup of patients receiving NP regimen." (PMID 28924235, 2017). "Polymorphisms in GTF2H1, ERCC2 and RPA1 showed significant association with anemia." (PMID 28924235, 2017). "The results showed that GTF2H1/P62 and DDB2 presented consecutive significant signals on anemia." (PMID 28924235, 2017).
colorectal cancer (1 paper, 2020). A primary or metastatic malignant neoplasm that affects the colon or rectum. "Single nucleotide polymorphisms (SNPs) in miRNA-binding sites in the NER genes RPA2 and GTF2H1 are associated with the risk of colorectal cancer (CRC)." (PMID 32629861, 2020).
cutaneous melanoma (1 paper, 2019). A primary melanoma arising from atypical melanocytes in the skin. "In primary human cutaneous melanomas, GTF2H1 expression positively correlated with clinical stage such as tumor thickness and depth of invasion indicating an association with tumor progression." (PMID 30651597, 2019). "Moreover, immunohistochemical analyses of a large panel of primary human cutaneous melanomas (n = 136) spotted onto tissue microarrays (TMA) revealed a moderate but significant correlation between MITF and GTF2H1 at the protein level." (PMID 30651597, 2019).
lung squamous cell carcinoma (1 paper, 2022). "In our study, it was found that GTF2H1 rs3802967 CT-TT reduced the risk of lung squamous cell carcinoma." (PMID 36384536, 2022). "Stratified by pathological type, GTF2H1 rs3802967 was associated with a reduced risk of lung squamous cell carcinoma (OR = 0.68, p = 0.045)." (PMID 36384536, 2022). "GTF2H1 rs3802967 was associated with the reduced risk of lung squamous cell carcinoma." (PMID 36384536, 2022). "In addition, GTF2H1 rs3802967 was associated with a reduced risk of lung squamous cell carcinoma." (PMID 36384536, 2022).
lymphoma (1 paper, 2023). A malignant (clonal) proliferation of B- lymphocytes or T- lymphocytes which involves the lymph nodes, bone marrow and/or extranodal sites. "These include the lymphoma related BCL11A gene, the IKZF2 gene involved in lymphocyte development or the transcription initiator GTF2H1." (PMID 36961799, 2023).
melanoma (1 paper, 2019). A malignant, usually aggressive tumor composed of atypical, neoplastic melanocytes. "Individual site-specific mutation at the E boxes reduced GTF2H1 promoter activity and combined site-specific mutations at all three E boxes increased the repressive effect on reporter activity as demonstrated in murine and human melanoma cells." (PMID 30651597, 2019). "The concordant expression of MITF and GTF2H1 transcripts was confirmed in several genetically heterogeneous melanoma lines by RT-PCR." (PMID 30651597, 2019). "In addition, forced expression of GTF2H1 was associated with an increase in proliferation of IHM and melanoma cells exhibiting a complete lack or low abundance of MITF, respectively." (PMID 30651597, 2019). "To assess whether depletion of GTF2H1 recapitulates the senescence-like phenotype induced by knockdown of MITF, we utilized several independent siRNAs directed against GTF2H1, which caused a significant growth inhibition in vitro in a variety of melanoma cell lines." (PMID 30651597, 2019).
microphthalmia (1 paper, 2019). Congenital or developmental anomaly in which the eyeballs are abnormally small. "Here we demonstrate that the Microphthalmia-associated transcription factor (MITF) directly controls general transcription and UVR-induced nucleotide excision repair by transactivation of GTF2H1 as a core element of TFIIH." (PMID 30651597, 2019).
neuroblastoma (1 paper, 2023). Neuroblastoma (NB) is the most common solid, extracranial childhood tumor. "GTF2B has been identified as a prognostic marker for colorectal cancer and neuroblastoma, while GTF2H1 is a p62 subunit of complex transcription factor IIH (TFIIH) that regulates nucleotide excision repair and transcription." (PMID 37260986, 2023).
cancer (7 papers, 2018 to 2025). A tumor composed of atypical neoplastic, often pleomorphic cells that invade other tissues. "Together, our results expose GTF2H1 as a potential novel predictive marker of platinum drug sensitivity in SWI/SNF-deficient cancer cells." (PMID 30287812, 2018). "As a result, GTF2H1 may be an important prognostic indicator of platinum drug susceptibility in SWI/SNF-deficient cancer cells." (PMID 35957812, 2022). "Therefore, reduced GTF2H1 expression may be a better predictive marker for platinum-drug sensitivity of SWI/SNF-deficient cancers." (PMID 30287812, 2018). "The authors of these studies concluded that the SNP variants influenced miRNA-mediated regulation of GTF2H1 and RPA2 mRNA levels and thus DNA repair activity and the cancer risk." (PMID 32629861, 2020). "We next tested GTF2H1 protein levels by IF in additional BRG1 and/or BRM-deficient cancer cell lines." (PMID 30287812, 2018). "GTF2H1 and ERCC6 regulate nucleotide excision repair, and their loss is expected to result in the compromised ability of cells in DNA repair, a hallmark of cancer progression." (PMID 41468516, 2025). "Based on our analysis, one such DDR deficiency could be impaired NER due to downregulation of GTF2H1 expression, rendering SWI/SNF cancers more sensitive to DNA damaging chemotherapeutic drugs such as cisplatin." (PMID 30287812, 2018). "These intriguing results could imply that cancer cells that have lost the activity of SWI/SNF subunit(s) may be differentially sensitive to DNA damaging chemotherapeutics depending on their GTF2H1 levels." (PMID 30287812, 2018). "As a consequence, DNA damage sensitivity of BRM- or BRG1-deficient cells correlates with GTF2H1 protein levels, which could, potentially, be used to select SWI/SNF-deficient cancers that are more sensitive to platinum drug chemotherapy." (PMID 30287812, 2018). "Five genes are involved in DNA repair, a role closely related to genome maintenance and cancer, and were shown to have a protective role in various types of cancer (only one paper is cited by gene, but many others confirm this role): EXO1, ERCC1, GTF2H1, MDC1, and DGCR8." (PMID 31568528, 2019). "Several factors involved in the NER pathway such as XPF and general transcription factor II H (GTF2H1) were enriched in TERRA-iDRiP-MS in ALT cancer cells but not in mouse embryonic stem cells, implying that NER factors have specific functions at ALT telomeres." (PMID 36184605, 2022).
GTF2H1 also shares sentences with these, for which no sentence is quoted: tumor (3 papers); Fanconi anemia (2); Sepsis (1).